DDIT3 (DNA damage inducible transcript 3)
Description:
Multifunctional transcription factor in endoplasmic reticulum (ER) stress response. Plays an essential role in the response to a wide variety of cell stresses and induces cell cycle arrest and apoptosis in response to ER stress. Plays a dual role both as an inhibitor of CCAAT/enhancer-binding protein (C/EBP) function and as an activator of other genes (By similarity). Acts as a dominant-negative regulator of C/EBP-induced transcription: dimerizes with members of the C/EBP family, impairs their association with C/EBP binding sites in the promoter regions, and inhibits the expression of C/EBP regulated genes (By similarity). Positively regulates the transcription of TRIB3, IL6, IL8, IL23, TNFRSF10B/DR5, PPP1R15A/GADD34, BBC3/PUMA, BCL2L11/BIM and ERO1L. Negatively regulates; expression of BCL2 and MYOD1, ATF4-dependent transcriptional activation of asparagine synthetase (ASNS), CEBPA-dependent transcriptional activation of hepcidin (HAMP) and CEBPB-mediated expression of peroxisome proliferator-activated receptor gamma (PPARG). Together with ATF4, mediates ER-mediated cell death by promoting expression of genes involved in cellular amino acid metabolic processes, mRNA translation and the unfolded protein response (UPR) in response to ER stress (By similarity). Inhibits the canonical Wnt signaling pathway by binding to TCF7L2/TCF4, impairing its DNA-binding properties and repressing its transcriptional activity. Plays a regulatory role in the inflammatory response through the induction of caspase-11 (CASP4/CASP11) which induces the activation of caspase-1 (CASP1) and both these caspases increase the activation of pro-IL1B to mature IL1B which is involved in the inflammatory response (By similarity). Acts as a major regulator of postnatal neovascularization through regulation of endothelial nitric oxide synthase (NOS3)-related signaling (By similarity). [Isoform AltDDIT3]: Product of the upstream open reading frame (uORF) of DDIT3/CHOP that is specifically produced in absence of stress, thereby preventing translation of downstream stress effector DDIT3/CHOP.
Synonyms: CHOP; CHOP-10; CHOP10; GADD153; AltDDIT3; C/EBPzeta; CEBPZ
Target class: Transcription factor
Gene: Protein-coding gene on chromosome 12 (57,516,588 to 57,521,737, reverse strand). Ensembl gene ENSG00000175197.
Subcellular location: Cytoplasm; Nucleus
Subcellular location (Human Protein Atlas): Nucleoplasm
Pathways (Reactome):
Cellular responses to stimuli: ATF4 activates genes in response to endoplasmic reticulum stress; ATF6 (ATF6-alpha) activates chaperone genes; Response of EIF2AK1 (HRI) to heme deficiency; Response of EIF2AK4 (GCN2) to amino acid deficiency
Gene expression (Transcription): FOXO-mediated transcription of cell death genes
Gene Ontology:
Molecular function: cAMP response element binding protein binding; DNA binding; DNA-binding transcription activator activity, RNA polymerase II-specific; DNA-binding transcription factor activity; identical protein binding; leucine zipper domain binding; protein binding; protein heterodimerization activity; protein homodimerization activity; RNA polymerase II cis-regulatory region sequence-specific DNA binding; RNA polymerase II-specific DNA-binding transcription factor binding; transcription cis-regulatory region binding; transcription corepressor activity; DNA-binding transcription factor activity, RNA polymerase II-specific; transcription regulator activator activity; transcription regulator inhibitor activity
Biological process: cell redox homeostasis; HRI-mediated signaling; integrated stress response signaling; intracellular signal transduction; intrinsic apoptotic signaling pathway in response to endoplasmic reticulum stress; negative regulation of determination of dorsal identity; negative regulation of DNA-templated transcription; negative regulation of interleukin-17 production; negative regulation of interleukin-4 production; negative regulation of phosphatidylinositol 3-kinase/protein kinase B signal transduction; negative regulation of transcription by RNA polymerase II; negative regulation of type II interferon production; positive regulation of DNA-templated transcription; positive regulation of endoplasmic reticulum stress-induced intrinsic apoptotic signaling pathway; positive regulation of interleukin-8 production; positive regulation of intrinsic apoptotic signaling pathway; positive regulation of neuron apoptotic process; positive regulation of transcription by RNA polymerase II; proteasome-mediated ubiquitin-dependent protein catabolic process; regulation of DNA-templated transcription; regulation of transcription by RNA polymerase II; response to endoplasmic reticulum stress; response to unfolded protein; anterior/posterior axis specification; ATF6-mediated unfolded protein response; and 20 more
Cellular component: CHOP-ATF3 complex; CHOP-ATF4 complex; CHOP-C/EBP complex; cytoplasm; nucleoplasm; nucleus; protein-DNA complex; RNA polymerase II transcription regulator complex; chromatin; cytosol; transcription regulator complex; late endosome
Genetic constraint (gnomAD): Loss-of-function variants: 14 observed, 18.43 expected, observed/expected ratio (o/e) 0.76, 90% interval 0.5 to 1.19. The upper end of that interval is the gene's LOEUF score, 1.19, which puts it in group 5 of 6, group 1 being the genes least tolerant of losing a copy. Missense variants: 216 observed, 209.23 expected, observed/expected ratio (o/e) 1.03, 90% interval 0.92 to 1.16. Synonymous variants: 93 observed, 80.13 expected, observed/expected ratio (o/e) 1.16, 90% interval 0.98 to 1.38.
Cancer hallmarks: tumour promoting inflammation (promotes); escaping programmed cell death (suppresses)
Homologues: Orthologues: chimpanzee DDIT3 (99% identical), macaque DDIT3 (98% identical), pig DDIT3 (95% identical), dog DDIT3 (92% identical), rabbit DDIT3 (91% identical), rat Ddit3 (91% identical), guinea pig DDIT3 (89% identical), mouse Ddit3 (88% identical), tropical clawed frog ddit3 (48% identical), zebrafish ddit3 (43% identical).
Diseases named in the same sentence as DDIT3 in open-access papers:
DDIT3 is named in the same sentence as 465 diseases in open-access papers, as found by Europe PMC text mining. Sharing a sentence is not in itself a finding about the gene and the disease. The quoted sentences say what the papers report.
breast carcinoma (110 papers, 2009 to 2026). "Intriguingly, DDIT3 overexpression has been correlated with a reduced risk of breast cancer recurrence." (PMID 38545201, 2024). "We leveraged publicly available datasets and bioinformatics tools to offer novel insights into the molecular mechanisms underlying DDIT3-mediated effects in breast cancer progression." (PMID 38911383, 2024). "We introduced a novel prognostic signature associated with DDIT3 expression, immune microenvironment modulation, and response to therapy in breast cancer." (PMID 38911383, 2024). "Identifying the DDIT3-related prognostic signature and its association with the immune microenvironment provided a promising avenue for personalized breast cancer treatment." (PMID 38911383, 2024). "DDIT3 expression pattern in breast cancer is associated with the clinical parameters." (PMID 38911383, 2024). "However, the impact of DDIT3 on breast cancer prognosis and its underlying mechanisms are unclear." (PMID 38911383, 2024). "Furthermore, the correlation between DDIT3 expression and the loss of heterozygosity, microsatellite instability, and neoantigen burden underscores its potential effect on genomic instability inherent to breast cancer." (PMID 38911383, 2024). "Consequently, high DDIT3 expression may be associated with increased invasiveness and metastatic potential in breast cancer, which are correlated with poorer prognosis." (PMID 38911383, 2024). "This study demonstrated the implications of DDIT3 in breast cancer, suggesting its role in disease progression, immune modulation, mutational landscapes, and potential treatment." (PMID 38911383, 2024). "In breast cancer, high DDIT3 expression is positively correlated with these pathways, reflecting the biological response of tumor cells to ER stress." (PMID 38911383, 2024). "Our findings improved our understanding of the role of DDIT3 in breast cancer and suggested promising applications in clinical practice." (PMID 38911383, 2024). "Our comprehensive investigation into the immunological effects and prognostic implications of DDIT3 in breast carcinoma has indicated its diverse functions and potential clinical application." (PMID 38911383, 2024). "Overall, our study not only facilitates understanding the role of DDIT3 in breast cancer but also offers innovative insights for developing prognostic models and therapeutic strategies." (PMID 38911383, 2024). "This multi-dimensional analysis provided a comprehensive understanding of the intricate interplay between DDIT3 and the immune microenvironment in breast cancer." (PMID 38911383, 2024). "We observed a strong correlation between DDIT3 expression and advancing breast cancer stages, thereby implying its role in tumor progression." (PMID 38911383, 2024). "For example, it was reported that high properdin expression in breast cancer induces apoptosis by upregulating the proapoptotic transcription factor DDIT3, which is related to the endoplasmic reticulum stress response." (PMID 37951917, 2023). "This compound results in the activation of ElF2A, HSP90B1/GRP94, HSPA5 and DDIT3 in HepG2 hepatoma and breast carcinoma MCF-7 cells." (PMID 36497321, 2022). "The general trend of the three HER2/neu-positive breast cancer cell lines tested was that they possessed higher basal levels of DDIT3/CHOP, ATF6 and spliced XBP1 and that these levels increased in response to palmitate treatment." (PMID 27464732, 2016). "Finally, the expression pattern of DDIT3 in breast cancer correlates with clinical parameters, increasing with advanced stages and suggesting its involvement in tumor progression." (PMID 40362379, 2025). "Moreover, researchers have reported the role of DDIT3 in cancer biology, particularly in breast cancer 3,7." (PMID 38911383, 2024). "However, we established a correlation between DDIT3 and adverse outcomes in patients with breast cancer." (PMID 38911383, 2024).
breast carcinoma (continued). "Importantly, the validation analysis accentuated the adverse correlation between elevated DDIT3 expression and recurrence-free survival in patients with breast cancer." (PMID 38911383, 2024). "In this study, we aimed to utilize bioinformatics to analyze the role of DDIT3 in breast cancer." (PMID 38911383, 2024). "scRNA data underscored widespread DDIT3 across various cell types within breast cancer." (PMID 38911383, 2024). "Conversely, in both breast cancer cell lines, O-desmethyltramadol consistently downregulated the expression of SLC16A1, CD22, NUPR1, ASNS, and DDIT3." (PMID 40362379, 2025). "Notably, RNA-Seq analysis revealed that AdipoR1 stimulation upregulated ferroptosis-related genes, DDIT3, HMOX1, and IRE1α, and downregulated proliferation-related genes, estrogen receptor and TROP2, in breast cancer cell lines." (PMID 41888104, 2026). "Additionally, a pan-cancer pathway analysis suggested that DDIT3 was positively correlated with apoptosis, cell cycle, DNA damage, and epithelial-mesenchymal transition (EMT) pathways in breast cancer." (PMID 38911383, 2024). "Unlike previous studies 11,39, we utilized an integrative bioinformatics approach coupled with IHC, which has not been extensively explored regarding the role of DDIT3 in breast cancer." (PMID 38911383, 2024). "This research highlights the potential of DDIT3 as a pivotal node for therapeutic interventions targeting the interplay between the tumor microenvironment and its non-neoplastic inhabitants in breast cancer." (PMID 38911383, 2024). "While latest studies 12 have shown that CFP up-regulates TES mediated transcription factor DDIT3 to inhibit the growth of breast cancer cells, the relationship between CFP and other tumors has not been reported." (PMID 33976747, 2021). "Notably, other HER2/neu-positive breast cancer cell lines, BT474 and HCC1569, have elevated DDIT3/CHOP mRNA levels under standard growth growth conditions." (PMID 27464732, 2016). "The increase in DDIT3 found in DOX-treated cardiomyocytes for 24 h suggests that the increase in MitoBax may promote ER stress-related changes in DDIT3, compared to breast cancer MCF7 cells that show increased DDIT3 in response to ER stress in response to DOX as early as 3 h." (PMID 36824370, 2023). "Besides, CTet was found to activate the ER stress response, as well as upregulate recombinant DNA damage-inducible transcript 3 (DDIT3)/C/EBP homologous protein (CHOP) and DDIT4, subsequently inhibiting mTOR expression, leading to the induction of autophagy in breast cancer cells." (PMID 36104717, 2022). "Second, we observed a significant upregulation of the gene DDIT3, but not DDIT4, after BB-CLA treatment in both feline and canine mammary cancer cell lines, which could indicate that BB-CLA is promoting activation of the apoptosis pathway rather than the autophagy pathway in response to ER stress." (PMID 29649984, 2018).
diabetes (105 papers, 2007 to 2025). "DDIT3, CHOP, or GADD153 protein functions as a dominant-negative inhibitor by forming heterodimers with other C/EBP members, such as C/EBP and is linked to diabetes." (PMID 24993133, 2014). "The ISR pathway that activates the GCN2/EIF2AK4 and CHOP/DDIT3 along with other genes may influence the development of age-associated diseases, including cancer, neurodegeneration, diabetes, other, and through them, lifespan and survival traits." (PMID 34825130, 2021). "Diabetes mellitus Apoe-knockout mice, supplemented with glucosamine, developed intracellular lipid accumulation, indicating the development of NAFLD, and that was associated with increased content of the UPR markers BIP, ENPL, DDIT3 and protein disulfide-isomerase in liver tissue." (PMID 35011666, 2021).
myxoid liposarcoma (93 papers, 2005 to 2026). A liposarcoma characterized by the presence of round non-lipogenic primitive mesenchymal cells and small signet ring lipoblasts within a myxoid stoma with a branching vascular pattern. "It has been shown in some studies that DDIT3 gene amplification is associated with myxoid liposarcoma-like morphology." (PMID 34089125, 2022). "However, targeted RNA NGS unveiled an EWSR1::DDIT3 gene fusion, which is pathognomonic and diagnostic for myxoid liposarcoma." (PMID 38137051, 2023). "For example, FISH testing for DDIT3 gene rearrangement can be used for the diagnosis of primary ovarian low-grade myxoid liposarcoma." (PMID 41450911, 2025). "The FUS/EWSR1-DDIT3 fusion characteristic of myxoid liposarcoma can be distinguished from LLT using DDIT3 immunohistochemistry, in which nuclear anti-DDIT3 immunoreactivity is a highly sensitive and specific marker of myxoid/round cell liposarcoma." (PMID 41230282, 2025). "The FET (FUS, EWSR1, and TAF15) fusion oncogenes are characteristic for around 20 different sarcomas and leukemia, including FUS::DDIT3 in myxoid liposarcoma (MLS) and EWSR1::FLI1 in Ewing sarcoma (EWS), the two most common FET sarcoma entities." (PMID 40988026, 2025). "Instead, FUS::DDIT3-bound SWI/SNF complexes in myxoid liposarcoma cells are enriched in PBAF and GBAF components as well as most interaction partners." (PMID 40988026, 2025). "Myxoid liposarcoma harbors FUS/EWSR1-DDIT3 fusions, and nuclear DNA damage-inducible transcript 3 (DDIT3) immunoreactivity is a highly sensitive and specific marker." (PMID 41230282, 2025). "Conversely, myxoid liposarcomas with DDIT3 translocations (FUS::DDIT3 fusion) generally respond better to radiotherapy, highlighting the variability in treatment responses based on specific genetic profiles." (PMID 39229483, 2024). "Three tumors were grade 1 myxoid liposarcomas (all with FUS::DDIT3 fusion transcript), and two tumors were grade 2 pleomorphic liposarcomas." (PMID 37370837, 2023). "The YAP1:TFE3-fused gene and WWTR1(TAZ)-CAMTA1 gene fusions are characteristic of haemangioendothelioma, whereas the presence of FUS:DDIT3 or EWSR1:DDIT3 genes is pathognomonic in myxoid liposarcoma (MLPS), a malignant tumour, recapitulating lipogenesis." (PMID 37681936, 2023). "Demonstration of DDIT3 rearrangement (FUS-DDIT3 or EWSR1-DDIT3 fusion genes) is also helpful in ruling out myxoid liposarcoma." (PMID 36810566, 2023). "Taking together the histology and immunohistochemistry results and the presence of a specific EWSR1::DDIT3 gene fusion, this case should be considered as a myxoid liposarcoma, at least of intermediate grade because of the increased cellularity in this biopsy." (PMID 38137051, 2023). "For instance, myxoid liposarcoma is characterized by DDIT3 translocation, most commonly fused with FUS gene, while extraskeletal myxoid chondrosarcoma features a recurrent NR4A3 translocation, most frequently translocated to EWSR1 gene." (PMID 35484289, 2022). "The genetic location of the myxoid liposarcoma is a repeated translocation of DDIT3 on chromosome 12, which produces a chimeric oncoprotein." (PMID 36233241, 2022). "Fused in sarcoma: DNA damage‐inducible transcript 3 protein (FUS:DDIT3) is a chimeric fusion oncoprotein present in 90% of human myxoid liposarcomas (MLS)." (PMID 30979710, 2019). "Furthermore, 15 specimens of myxoid liposarcomas were tested either for FUS BrAp or DDIT3 break-apart signals, and seven were found to be positive for these translocations (four cases for FUS BrAp and three for DDIT3 BrAp)." (PMID 40718211, 2025). "A few studies tested the MDM2 gene and DDIT3 fusion gene to distinguish between liposarcoma and myxoid liposarcoma (MLS), but no deletions or mutations were identified." (PMID 41458523, 2025). "Immunohistochemically, myxoliposarcomas can be differentiated by DDIT3 reactivity." (PMID 40729281, 2024). "In particular, DDIT3 shows strong high expression in myxoid liposarcoma tissues." (PMID 36233241, 2022).